TRPV1 (transient receptor potential cation channel subfamily V member 1)
Diseases named in the same sentence as TRPV1 in open-access papers (continued):
Sharing a sentence is not in itself a finding about the gene and the disease.
neuropathy (continued). "Altogether, these results suggest that JI017 may be a potent candidate for the management of oxaliplatin-induced neuropathy as it decreases pain, spinal TRPV1, and astrocyte activation." (PMID 34445514, 2021). "Both TRPV4 and TRPV1 have been suggested to contribute to paclitaxel-induced neuropathy." (PMID 33105614, 2020). "CGRP(+) IENFs compensate for the thermal withdrawal after TRPV1 depletion in RTX neuropathy." (PMID 30578250, 2019). "Peripheral inflammation or neuropathy upregulated TRPV1 expression in DRG nociceptive neurons, and knockdown of TRPV1 expression or TRPV1 antagonists significantly inhibited inflammation-induced or nerve injury-induced thermal hyperalgesia and mechanical allodynia." (PMID 22870919, 2012). "Further, the results suggest that enhanced expression and inflammation-induced sensitization of TRPV1 at the spinal cord may play a role in central sensitization in STZ-induced neuropathy." (PMID 21794120, 2011). "Thus, TRPV1 antagonists could further be used to relieve chronic pains experienced in neuropathy and cancer, and, as an example, PnTx3-5 treatment may overcome the use of morphine due to its absence of in vivo side effects, such as locomotor disorder or tolerance." (PMID 39998081, 2025). "By using the mouse model of CDDP-induced neuropathy, researchers found that treatment with CDDP results in an increase of TRPV1 mRNA level in cultured DRG neurons and the similar up-regulation of TRPV1 occurs in CDDP-treated mice." (PMID 35153744, 2021). "TRPV1 and TRPA1 expression in nociceptors are altered in different models of neuropathy under pathological conditions." (PMID 32613759, 2020). "RTX is an ultrapotent capsaicin analog that sensitizes TRPV1 and our previous studies have characterized the neuropathic manifestation of RTX neuropathy model." (PMID 30578250, 2019). "Our previous studies revealed that neuropathy was obvious after 8 weeks in the mice with STZ-induced DM, in which both TRPV1 and CGRP were impaired in DM heart and subsequently increased the MI-induced injury." (PMID 27252827, 2016). "Taken together, fewer CGRP(+) neurons were colocalized with TRPV1(+) neurons than SP(+) neurons and these were resistant to RTX-induced neuropathy." (PMID 23209829, 2012). "This is the first study to describe sensitization of TRPV1 and TRPA1 and/or TRPM8 in a model of oxaliplatin induced neuropathy, the role of cAMP in mediating the sensitization, and the effectiveness of a CB2 agonist in mitigating it." (PMID 21106058, 2010). "To investigate this, we explore the possible involvement of TRPV1 and the MOR-NMDAR complex in the antiallodynic effect of LMH-2 in a mouse model of neuropathy induced by hyperglycemia, as well as the possible interaction of LMH-2 with TRPV1 in silico through docking analysis." (PMID 40266532, 2025). "Genetic ablation of TRPV1+ neurons or chemical ablation or desensitization of TRPV1+ afferents neither prevented nor attenuated mechanical hyperalgesia following neuropathy." (PMID 32404326, 2020). "As in our previous findings, TRPV1(+) neurons were completely depleted (80.1±16.7 versus 1.0±1.3 neurons/mm2; P<0.001), and mild depletion was present in PAP(+) neurons (291.9±24.0 versus 196.2±16.3 neurons/mm2; P<0.001) after RTX neuropathy due to PAP and TRPV1 colocalization." (PMID 30578250, 2019). "Despite the involvement of RAGE-dependent PKC activation in sensory neurons of diabetic animal models, its role in modulating TRPV1 as a contributor to neuropathy has not been considered so far." (PMID 29474476, 2018). "TRPV1 and SP are known molecular mediators of thermal sensations and are responsible for the induction of thermal hypoalgesia in RTX-induced neuropathy." (PMID 23209829, 2012). "In painful neuropathies, intraepidermal TRPV1 nerve fibre expression is low or absent, suggesting that pain generated is not directly related to sensory nerve fibres." (PMID 17927589, 2007).
Hypertension (48 papers, 2010 to 2026). The presence of chronic increased pressure in the systemic arterial system. "The variation of TRPV1, rs4790522, was associated with a higher salt recognition threshold in people with hypertension and obesity." (PMID 37185752, 2023). "Consistently, TRPV1 activation reportedly protects against renal damage during hypertension as TRPV1 loss promotes the upregulation of fibronectin, expression of type I and III collagen, which can delay the progression of interstitial renal fibrosis." (PMID 36045746, 2022). "The risk of having hypertension among the TT genotype of TRPV1, rs8065080 gene was approximately two times higher than that of individuals possessing one or more C alleles (CC and CT) with a 95% confidence interval of 1.14–3.13 (P=0.016)." (PMID 34150338, 2021). "Participants that were homozygous TT for TRPV1, rs8065080 had approximately two times higher the risk of having hypertension than that of carriers of the C allele." (PMID 34150338, 2021). "The risk of having hypertension among individuals having the TT genotype of TRPV1, rs8065080 was approximately two times higher than that of carriers of the C allele." (PMID 34150338, 2021). "On the other hand, intravenous infusion of the TRPV1 agonist capsaicin was previously shown to cause a hypertension and tachycardia in anesthetized dogs." (PMID 20932337, 2010). "In conclusion, our results demonstrate that intravenous infusion of the TRPV1 agonist DHC to healthy rats causes an initial hypertension and tachycardia." (PMID 20807439, 2010). "Furthermore, the thermosensitive receptors, TRPA1/TRPM8/TRPV1, which are expressed in the cardiovascular system, have been implicated in the pathogenesis of hypertension." (PMID 38255767, 2024). "Another polymorphism of TRPV1, rs8065080, was connected to a risk of hypertension." (PMID 37185752, 2023). "Interestingly, inflammatory cytokine responses in induced dietary salt linked forms of hypertension are modified in TRPV1 knockout mice (TRPV1−/−; Wang and Wang, 2009)." (PMID 23335875, 2012). "It is used to study functional and therapeutic properties of TRPV1 in diseases related to pain, cardiovascular disease, hypertension, and breast cancer, among others." (PMID 40867862, 2025). "Since a recent study in WT and Trpv1−/− rats suggested sex impacted the hemodynamic response to 2K1C hypertension, the data are presented separately for male and female mice." (PMID 41394927, 2025). "A recent study by Stocker & Sullivan (2023) showed that deletion of TRPV1 channels in the 2K1C model of renal injury and hypertension in rats restored elevated renal afferent nerve activity and attenuated the degree of sympatho‐excitation and hypertension." (PMID 40349310, 2025). "A recent study utilising TRPV1 gene‐deleted rats showed an attenuated sympathoexcitation, hypertension and improved glomerular filtration in the 2‐kidney‐1‐clip (2K1C) rat model of renal injury and hypertension." (PMID 40349310, 2025). "Chemical ablation of renal sensory nerves using agonists for transient receptor potential vanilloid-1 (TRPV1) lowers arterial blood pressure (ABP) in multiple experimental models of hypertension." (PMID 41394927, 2025). "A second major goal of the present study was to assess the extent by which TRPV1 channels contributed to sympathoexcitation and hypertension in a mouse 2K1C renovascular hypertension model." (PMID 41394927, 2025). "The effect of dietary capsaicin on experimental hypertension was studied in wild-type and TRPV1-null (Trpv1−/−) male C57BL/6J mice." (PMID 37240118, 2023). "In conclusion, our present results showed that warm needle acupuncture produces an antihypertensive effect by activating C-fibers in the median nerve through peripheral TRPV1 activity in a rat model of immobilization stress-induced hypertension." (PMID 37384285, 2023).
Hypertension (continued). "Taken together, the OLDA treatment prevented the occurrence of renal injury and hypertension in HFD-fed rats probably via protecting the TRPV1-positive afferent renal nerves first, and then recovering the suppressing effects of ARNA on RSNA." (PMID 37047183, 2023). "Our previous studies showed that dietary capsaicin, a specific agonist of TRPV1, triggers nitrogen oxide production in vascular endothelial cells, thus improving endothelial-dependent vasodilation to protect against hypertension." (PMID 35043013, 2022). "Risk for hypertension was observed in two polymorphisms, specifically SCNN1B, rs239345, and TRPV1, rs8065080." (PMID 34150338, 2021). "To fill these gaps, therefore, we will investigate the detailed molecular mechanism of HDR-2 on phenotypic switching and proliferation of VSMCs and chronic activation of TRPV1 in hypertension." (PMID 34711215, 2021). "Meanwhile, TRPV1, V3 or V4 likely play a protective role in systemic hypertension and atherosclerosis, since they participate in NO release via endothelium and metabolism lipid regulation." (PMID 32854408, 2020). "Various animal models of HF including post-infarction-, high salt diet/hypertension-, pressure overload-, or toxic cardiac injury (e.g., doxorubicin)-induced models showed important roles of TRPV1 in HF." (PMID 32586044, 2020). "Until the apparent disconnect between animal experiments and human studies are dissolved, patients taking TRPV1 antagonists should be carefully monitored for sepsis, hypertension, renal, and cardiovascular inflammation." (PMID 31344877, 2019). "Our studies demonstrated that the activation of TRPV1 by dietary capsaicin can attenuate genetic and high-salt diet induced hypertension." (PMID 27120617, 2016). "Activation of TRPV1 by capsaicin exerts an anti-hypertension effect by promoting the release of calcitonin gene-related peptide (CGRP) from capsaicin-sensitive nerves and nitric oxide (NO) from endothelial cells." (PMID 27120617, 2016). "Chronic dietary capsaicin ameliorated excess salt consumption-induced vascular dysfunction and nocturnal hypertension by inhibiting vascular oxidative stress in a TRPV1-dependent manner." (PMID 27120617, 2016). "In a work studying the contribution of the capsaicin receptor TRPV1 in HS diet-induced hypertension, a 8% salt in the diet increased significantly the BP of control animals only during the dark i.e. activity period." (PMID 27088730, 2016). "Given the potential differences in Trpv1 expression between species and especially rodents, the current study assessed the proportion of TRPV1 mouse renal sensory neurons and also tested the contribution of TRPV1 channel in 2K1C hypertension using wild-type (WT) and Trpv1−/− mice." (PMID 41394927, 2025). "Deletion of the TRPV1 channel attenuated the hypertension in male rats only." (PMID 41394927, 2025). "Several factors may contribute to the differential impact of 2K1C hypertension in the Trpv1−/− rat versus mouse." (PMID 41394927, 2025). "Activation of H4R in the RVMM elicited depressor and bradycardic responses in normotensive rats and mitigated hypertension in both models by exciting RVMM neurons through transient receptor potential vanilloid 1 (TRPV1)‐mediated pathways, thereby reducing renal sympathetic nerve activity (RSNA)." (PMID 41017599, 2025). "Additionally, the degeneration of TRPV1-filled nerves enhances salt-induced hypertension in rats after renal ischemia–reperfusion injury through the release of inflammatory mediators." (PMID 38255865, 2024). "Moreover, stimulation with 48°C WAI and a patch containing 1% capsaicin, a TRPV1 agonist, inhibited the development of hypertension in IMH rats." (PMID 37384285, 2023). "Clinical studies with the already available potent and selective small molecule TRPV1 antagonists may provide the answer to the opening question of this review: can TRPV1 represent a novel therapeutic target in hypertension?" (PMID 37240118, 2023).
Hypertension (continued). "However, using an in vivo rodent hypertension model, the transient receptor potential vanilloid 1 (TRPV1) channel was proven to be involved in RGC apoptosis induced by long pressure stress (+70 mmHg for 48 h), likely through the inflow of extracellular Ca2+." (PMID 35177963, 2022). "TRPV1 activation improves endothelial function, increases endothelium nitric oxide (NO) production, improves vasorelaxation, and may prevent hypertension." (PMID 34069822, 2021). "Moreover, the polymorphism of TRPV1, rs8065080, and SCNN1B, rs239345, genes were associated with a risk of hypertension (P=0.016 and P=0.024)." (PMID 34150338, 2021). "Thus, endothelial TRPV1 activation can be considered a potential strategy for the management of hypertension." (PMID 34711215, 2021). "TRPVs: Studies using TRPV1, V4-KO mice and pharmacological compounds that selectively target both channels, suggested that they regulate blood pressure and play a protective role against hypertension." (PMID 32854408, 2020). "By contrast, TRPV1 and V4 seem to play a protective role against hypertension." (PMID 32854408, 2020). "Moreover, TRPV1 activation by capsaicin inhibited hypertension-induced VSMCs phenotypic switching, reduced the intracranial arteriole remodeling and improved the endothelial production of NO in rats, which prevented hypertension." (PMID 32854408, 2020). "Additionally, activation of TRPV1 (transient receptor potential vanilloid subtype 1, a capsaicin receptor) by capsaicin prevents salt-induced kidney damage and hypertension after renal ischemia-reperfusion injury in rats." (PMID 31817083, 2019). "TRPV1 is involved in hypertension and its related target organ dysfunction." (PMID 27120617, 2016). "Emerging evidence suggests that TRPV1 may be an important sensor and regulator of cardiovascular homeostasis and a protector against certain cardiovascular diseases such as hypertension, endothelial dysfunction, and stroke." (PMID 23878415, 2013). "Our results demonstrate that topical administration of capsaicin (CS), a known TRPV1 agonist, effectively mitigates these pathological processes in a rat model of L-NAME-induced hypertension." (PMID 40867862, 2025). "There is a growing body of evidence in the literature highlighting the involvement of TRP channels, including TRPM7/8, TRPV1, and TRPA1, in the pathophysiology of hypertension." (PMID 38255767, 2024). "The tail blood pressure of UCP1−/− mice was higher than that of WT and TRPV1−/− mice after the 8th month, and TRPV1 knockout further accelerated and elevated the development of hypertension in a UCP1 knockout background." (PMID 35043013, 2022). "Activation of TRPV1 and eNOS by Br-RUT suggests its potential for preventing vasorelaxation/hypertension." (PMID 24369537, 2013). "Although the proportion of Trpv1-expressing renal sensory neurons differ between the rat and mouse this is unlikely to explain the differential effect on 2K1C hypertension in Trpv1−/−." (PMID 41394927, 2025). "In the present study, 2K1C hypertension was ∼130 mmHg mean ABP and unaffected in Trpv1−/− mice." (PMID 41394927, 2025). "The present study tested the hypothesis that activating the transient receptor potential vanilloid 1 (TRPV1) channel in afferent renal nerves suppresses RSNA and prevents renal dysfunction and hypertension in obese rats." (PMID 37047183, 2023). "OLDA, given intrathecally to segments supplying the kidney, prevented HFD-induced impairment in TRPV1-positive afferent renal nerves, resulting in the restoration of the suppressive effects of ARNA on RSNA and the alleviation of renal dysfunction and hypertension." (PMID 37047183, 2023). "In this study, we found that TRPV1 knockout alone did not increase ROS production or the occurrence of hypertension in WT mice, but the knockout of TRPV1 further exacerbated ROS production in the BAT of UCP1 knockout mice." (PMID 35043013, 2022).
Hypertension (continued). "However, in UCP1 knockout mice, when the inhibitory effect of TRPV1 on LETM1 disappeared, the knockout of TRPV1 reversely aggravated mitochondrial calcium disorder and subsequent ROS production in BAT, which led to the development of hypertension." (PMID 35043013, 2022). "Besides, TRPV1 at sensory nerve termini can be upregulated by inflammatory cytokines to release the proinflammatory neuropeptides CGRP and SP, which can promote hypertension by disturbing the balance between vascular contraction and relaxation." (PMID 31189399, 2019). "Activation of transient receptor potential vanilloid type 1 (TRPV1), a ligand-gated cationic channel, by EVO in endothelial cells may protect against certain cardiovascular diseases (CVDs) such as hypertension and stroke." (PMID 24369537, 2013). "Therefore, TRPV1-expressing sensory fibers contribute to 2K1C hypertension in both species; however, the TRPV1 channel does not contribute to 2K1C hypertension in the mouse." (PMID 41394927, 2025). "Animal experiments suggest a role for TRPV1 in hypertension, but human validation is still absent." (PMID 37240118, 2023). "TRPV1 knockdown exacerbates renal damage and fibrosis induced by DOCA salt-mediated hypertension; thus, TRPV1 may be a part of a protective mechanism against hypertension-induced organ damage." (PMID 36045746, 2022). "However, whether there exists any relationship between TRPV1 and LETM1 that regulates both cellular Ca2+ homeostasis in adipose tissue and how they cooperate in the development of hypertension are still unclear." (PMID 35043013, 2022). "For example, the activation of C-fibers by injecting capsaicin, a transient receptor potential vanilloid 1 (TRPV1) agonist, or mustard oil, a TRP ankyrin 1 (TRPA1) agonist, into the skin with neurogenic inflammation over the median nerve blocks the development of hypertension in rats." (PMID 32039692, 2020). "In rats, however, although the TRPV1 agonist capsaicin induced similar hypertension as anandamide or methanandamide, only the non-selective TRPV blocker ruthenium red but not the TRPV1 antagonist capsazepine was able to inhibit the pressor response to anandamide." (PMID 23308211, 2013).